FGF23 (fibroblast growth factor 23)
Diseases named in the same sentence as FGF23 in open-access papers (continued):
Sharing a sentence is not in itself a finding about the gene and the disease.
chronic kidney disease (continued). "It was revealed that blood FGF23 levels started to increase early in the progression of chronic kidney disease (CKD), before the increase in the blood phosphate level." (PMID 35216490, 2022). "Fibroblast growth factor 23 (FGF23) concentrations rise after the early stages of chronic kidney disease (CKD)." (PMID 36498673, 2022). "FGF23 levels started to increase early in the course of chronic kidney disease (CKD), which occurs before the increase of blood phosphate level." (PMID 35966090, 2022). "In chronic kidney disease (CKD), FGF-23 levels increase as a means to maintain normal serum phosphate homeostasis." (PMID 35613118, 2022). "Furthermore, the decreased expression of Kloth protein in chronic kidney disease allows for increased levels of fibroblast growth factor-23 (FGF-23), which in turn leads to decrease calcitriol synthesis and causes secondary hyperparathyroidism; leading to abnormal bone reconstruction." (PMID 36404305, 2022). "Therefore, the hypothesis that the serum FGF23 level could outrun first biochemical symptoms of calcium–phosphate imbalance in patients with early stages of chronic kidney disease is justified." (PMID 34258392, 2021). "Elevated FGF23 levels are an early progressive and common complication of chronic kidney disease (CKD)." (PMID 34901023, 2021). "SHPT is a chronic kidney disease- (CKD-) mineral and bone disorder and is characterized by alterations in serum calcium, phosphate, intact parathyroid hormone (iPTH), vitamin D, and FGF23; bone abnormalities; and vascular calcification." (PMID 33868402, 2021). "The circulating hormone FGF23 is best known as a phosphaturic hormone, with serum levels rising exponentially in chronic kidney disease (CKD), including in the early stages of CKD." (PMID 33534825, 2021). "High levels of Fgf23, on the other hand, are observed in patients with chronic kidney disease (CKD) and hypophosphatemic Ricketts, which lead to poor bone quality, osteomalacia, and disrupted skeletal homeostasis." (PMID 33057033, 2020). "It has been shown that circulatory Klotho levels are significantly lower in patients with chronic kidney disease (CKD) whereas FGF‐23 is elevated." (PMID 32686906, 2020). "Also, it was shown that in chronic kidney disease patients treated with hemodialysis, FGF23 could predict the progression of secondary hyperparathyroidism." (PMID 32398014, 2020). "Therefore, parathyroid FGFR1 and klotho expression is decreased in experimental SHP and in end-stage renal disease patients, and this may lead to resistance of the parathyroids to FGF23 in SHP." (PMID 32570711, 2020). "Chronic kidney disease‐mineral and bone disorder (CKD‐MBD) in dogs is associated with hypovitaminosis D, increased parathyroid hormone (PTH), and increased fibroblast growth factor‐23 (FGF‐23) concentrations." (PMID 33128421, 2020). "Due to important alterations in phosphate balance in chronic kidney disease (CKD), most research on FGF23 up until now was focused on CKD (see section “EPO, Iron, CKD, and Inflammation Are Important Regulators of iFGF23 Cleavage”)." (PMID 30971944, 2019). "In patients with chronic kidney disease (CKD), serum FGF-23 levels increase as compensatory mechanisms fail, even before serum phosphate levels rise." (PMID 31246994, 2019). "In chronic kidney disease (CKD), FGF23 is a well characterized prognostic marker not only for progression of CKD but also for increased systemic inflammation and mortality in these patients." (PMID 31075857, 2019). "Likewise, the discovery of FGF23 has led to further insights into the pathogenesis of chronic kidney disease–mineral and bone disorder (CKD-MBD), accounting for the paradigm shift from the classic trade off hypothesis to an updated trade off hypothesis." (PMID 31107896, 2019). "So far, FGF-23 in the pediatric population has been assessed mainly in children with chronic kidney disease (CKD)." (PMID 31354894, 2019).
chronic kidney disease (continued). "FGF-23 levels increase early in the course of chronic kidney disease (CKD), and precede the rise in serum phosphate and parathyroid hormone (PTH) level." (PMID 30428848, 2018). "The massively elevated serum levels of intact FGF23, as observed in late stages of chronic kidney disease (CKD), seem to result from an increase in FGF23 synthesis accompanied by an inhibition of FGF23 cleavage." (PMID 29770125, 2018). "Amgen has studied the effect of FGF23 monoclonal antibody on chronic kidney disease-mineral and bone disorder (CKD-MBD) using a rat model." (PMID 29949887, 2018). "Circulating intact FGF23 is also elevated in patients with chronic kidney disease (CKD), and can reach blood levels as high as 1,000-fold above the normal range." (PMID 29892265, 2018). "Fibroblast growth factor-23 (FGF23) is an established biomarker of adverse outcomes in patients with chronic kidney disease (CKD)." (PMID 29740119, 2018). "In ADPKD adults in chronic kidney disease (CKD) stages 1–2, FGF23 levels were highly increased compared to both healthy controls and CKD matched controls." (PMID 29326910, 2017). "Increase in FGF-23 concentration is accompanied by Klotho reduction as chronic kidney disease (CKD) worsens." (PMID 28130714, 2017). "Furthermore, some studies even show that elevated FGF-23 levels were associated with an increased risk for cardiovascular death, regardless of chronic kidney disease." (PMID 28792535, 2017). "The regulation of fibroblast growth factor-23 (FGF23) secretion in patients with chronic kidney disease (CKD) is incompletely understood." (PMID 27495287, 2016). "A previous multicenter study in the USA8 involving 3756 participants with mild to moderate chronic kidney disease (CKD) reported that diabetes patients had higher serum FGF23 levels and experienced an earlier onset of FGF23 excess." (PMID 27698482, 2016). "In the course of chronic kidney disease (CKD), plasma FGF23 concentration rises early, most probably to compensate the inability of the deteriorating kidneys to excrete an adequate amount of phosphate." (PMID 27941640, 2016). "Serum concentrations of fibroblast growth factor 23 (FGF23) rise early in the course of chronic kidney disease (CKD) and are strongly correlated with adverse clinical outcomes." (PMID 27852236, 2016). "Phosphate burden in chronic kidney disease (CKD) leads to elevated serum fibroblast factor-23 (FGF-23) levels, secondary hyperparathyroidism and chronic kidney disease-mineral bone disorder (CKD-MBD)." (PMID 26186634, 2015). "Although well known for PTH and in the setting of hyperphosphatemia in chronic kidney disease (CKD), only scarce data are available on the effect of acute hyperphosphatemia on FGF-23 levels." (PMID 25790436, 2015). "In chronic kidney disease (CKD), the accumulation of P stimulates FGF23 production from the early stages of CKD." (PMID 27081473, 2015). "In patients with chronic kidney disease (CKD), FGF-23 levels are usually elevated and can reach up to 300 – 400 times the normal range." (PMID 25208316, 2014). "The possibility that the FGF23/α-Klotho system mediates the aggravated cardiovascular outcome among patients with chronic kidney disease (CKD) has been suggested." (PMID 25200959, 2014). "Besides FGF-23 being a biomarker of phosphate metabolism, we believe that it might also be a biomarker for chronic kidney disease." (PMID 25295189, 2014). "As kidney function decreases in chronic kidney disease (CKD) patients, FGF23 increases progressively in order to regulate phosphate homeostasis." (PMID 23705925, 2013). "Serum concentration of fibroblast growth factor 23 (FGF23) increases in parallel with parathyroid hormone (PTH) as renal function declines in chronic kidney disease (CKD) to maintain phosphate and calcium homeostasis." (PMID 23587028, 2013).
chronic kidney disease (continued). "Several previous studies have analyzed the relationship between circulating FGF23/α-Klotho levels in the general population and in subjects with chronic kidney disease (CKD) and more advanced renal failure." (PMID 24039882, 2013). "Furthermore 2% of LC children had FGF23 concentrations over 1000 RU/ml, which are concentrations generally only reported in patients with clinical pathologies such as hereditary hypophosphatemic rickets and chronic kidney disease." (PMID 22465847, 2012). "Chronic kidney disease (CKD) leads to metabolic and cardiovascular complications, and the dysregulation of key biomolecules, namely fibroblast growth factor 23 (FGF23) and Klotho, plays a central role." (PMID 42072635, 2026). "On the other hand, antagonizing FGF23 or inhibiting FGFR4 may block the pro-hypertrophic effects of excess FGF23, especially relevant in conditions like chronic kidney disease (CKD) and HHD." (PMID 40362262, 2025). "In patients with chronic kidney disease (CKD) and other MBDs, elevated FGF23 levels lead to hypophosphatemia and abnormal vitamin D metabolism, ultimately impairing normal mineral deposition and exacerbating skeletal pathology." (PMID 40290428, 2025). "Although FGF23 has also been associated with CVD both in the general population and in the chronic kidney disease (CKD) population, whether this hormone contributes to the progression of atherosclerosis is still a matter of research." (PMID 41302941, 2025). "In end-stage renal disease (ESRD), despite extremely high FGF23 concentrations, almost all particles are biologically active." (PMID 40869274, 2025). "In addition to FGF-23, intact parathyroid hormone (iPTH) and homocysteine (Hcy) also play a role in the chronic kidney disease (CKD)-related mineral bone disease (MBD) process." (PMID 40612843, 2025). "Chronic kidney disease (CKD) results in hyperphosphatemia, enhanced tubular phosphate load and increased synthesis of fibroblast growth factor 23 (FGF23), which is discussed to contribute to inflammation and disease progression." (PMID 41384828, 2025). "In early-stage chronic kidney disease, compensatory increases in parathyroid hormone (PTH) and fibroblast growth factor-23 (FGF-23) levels maintain serum phosphate within normal ranges by enhancing renal excretion." (PMID 41166265, 2025). "Both FGF23 and α-KLOTHO are recognized as early markers of chronic kidney disease (CKD) and its progression, particularly in children with CAKUT." (PMID 40563451, 2025). "Chronic kidney diseases (CKD) results from decreased levels of Klotho and increased levels of FGF23 in the serum." (PMID 39066929, 2024). "1-α-hydroxylase, the rate-limiting enzyme pool, is sufficient until end-stage renal disease, claiming PTH and FGF-23 as the principal determinants of calcitriol levels." (PMID 38785509, 2024). "Mineral and bone disorder (MBD) in chronic kidney disease (CKD) comprises abnormalities in mineral metabolites and hormones, including serum calcium, phosphate, fibroblast growth factor-23, and parathyroid hormone (PTH), as well as bone disorder and vascular calcification." (PMID 38820324, 2024). "Notable among these are soluble α-Klotho and fibroblast growth factor-23 (FGF23), which show promise as biomarkers for chronic kidney disease." (PMID 38792509, 2024). "In human chronic kidney disease (CKD), elevated levels of FGF‐23 have been shown to be related to adverse health outcomes." (PMID 38923840, 2024). "This suggests a distinct adverse impact of FGF23 in XLH, a condition characterized by hypophosphatemia, compared to its role in chronic kidney disease, a condition complicated by hyperphosphatemia, uremia, and volume overload." (PMID 38818505, 2024). "Serum FGF23 is increased in chronic kidney disease (CKD) and contributes to pathologic cardiac hypertrophy by activating FGF receptor (FGFR) 4 on cardiac myocytes, which might lead to the high cardiovascular mortality in CKD patients." (PMID 39452290, 2024).
chronic kidney disease (continued). "Fibroblast growth factor 23 (FGF23) levels are often elevated in chronic kidney disease (CKD)." (PMID 38791495, 2024). "In the context of chronic kidney disease (CKD), rising FGF23 levels accompany declining kidney function, leading to hyperphosphatemia and cardiovascular complications, including LVH and arterial stiffness." (PMID 38846254, 2024). "Here, we set out to describe the role of FGFR modulator Memo1 in the osteoblast and in bone‐derived FGF23 expression under experimental AKI, based on reports that FGFR‐Klotho signaling is required for FGF23 expression during chronic kidney disease in mice." (PMID 36967231, 2023). "During chronic kidney disease (CKD) progression, an increase in fibroblast growth factor (FGF23) is present." (PMID 37762869, 2023). "The clinical importance of FGF23 has been extensively studied in chronic kidney disease (CKD)." (PMID 36829583, 2023). "Increased serum P stimulates FGF-23 and PTH, which play a role in cardiovascular disease mortality and hypertension, especially in patients with chronic kidney disease." (PMID 38137499, 2023). "Especially in chronic kidney disease (CKD) and cardiovascular disease, FGF23 predicts outcome." (PMID 37225713, 2023). "This association may be related to pathophysiological alterations in chronic kidney disease, such as secondary hyperparathyroidism, altered metabolism of the active form of vitamin D, phosphorus retention, chronic metabolic acidosis, increased levels of sclerostin and FGF23." (PMID 37507659, 2023). "In mice with chronic kidney disease (CKD), Phd1-3 enzymes were suppressed, consistent with FGF23 upregulation in this model." (PMID 36650133, 2023). "The earliest change found in chronic kidney disease (CKD) patients is a decrease in klotho expression, which subsequently leads to a state of resistance, with a compensatory increase in FGF23 preceding the increase in phosphatemia." (PMID 35612845, 2022). "Multiple FGFs have been shown to be elevated in patients with chronic kidney disease, including FGF21 and FGF23." (PMID 35215435, 2022). "FGF23 upregulates interleukin (IL)-6 and C-reactive protein (CRP) expression in the liver, thereby promoting inflammation in chronic kidney disease." (PMID 35084563, 2022). "Meanwhile, potential off-target effects on the cardiovascular, immune, and central nervous systems cannot be ignored given high FGF23 levels in vivo, especially in XLH patients with chronic kidney disease." (PMID 36060934, 2022). "We randomly recruited 118 patients with T1D with a normal or mildly impaired kidney function [chronic kidney disease (CKD) stages of G1/G2, A1/A2], and measured their serum FGF23 levels." (PMID 36084108, 2022). "Our previous study revealed that FGF23, a FGF family member related to chronic kidney disease-induced AF, increases PV arrhythmogenesis due to Na+ and Ca2+ dysregulation and mitochondrial ROS genesis via the activation of PKC signaling." (PMID 35118146, 2021). "This comprised three groups: FGF23‐dependent hypophosphatemia (n = 27), hypoparathyroidism (HOPT; n = 17), and chronic kidney disease (n = 30)." (PMID 33615106, 2021). "In patients with chronic kidney disease (CKD), FGF23 levels rise spontaneously in response to hyperphosphatemia." (PMID 35299844, 2021). "During chronic renal failure, patients develop bone mineralization abnormalities due to changes in hormone expression (i.e., PTH, FGF23 and vitamin D) that control mineral homeostasis and osteoblast/-clast function." (PMID 34452102, 2021). "Beyond its role as a phosphataemic regulator, circulating FGF23 is a strong predictor of disease progression and mortality in patients with chronic kidney disease (CKD), in whom higher levels of this hormone are prevalent, with an emerging role in cardiovascular disease." (PMID 34208131, 2021). "Particularly in chronic kidney disease (CKD), changes in FGF23 level can be detected very early and correlate with outcome." (PMID 35011602, 2021).
chronic kidney disease (continued). "In some patients with chronic kidney disease, high serum phosphate was observed in spite of high serum PTH and FGF23 level." (PMID 32398014, 2020). "In chronic kidney disease (CKD) progressive loss of renal capacity disrupts this axis over‐time, with marked changes in circulating calcium, phosphate, PTH, and fibroblast growth factor‐23 (FGF‐23)." (PMID 33190417, 2020). "In chronic kidney disease (CKD), high FGF23 plasma levels are observed prior to hyperparathyroidism or hyperphosphatemia." (PMID 33520985, 2020). "Similarly, a study in the Japanese population with early chronic kidney disease (CKD) reported that an FGF23 level of 56.8 pg/mL was the optimal cut-off point for vertebral fracture prediction." (PMID 32155909, 2020). "Throughout these hormonal alterations, serum phosphate levels gradually increase and by end-stage renal disease (ESRD), ultimately culminate in overt hyperphosphatemia due to renal resistance to FGF23′s actions on impaired kidneys." (PMID 31461904, 2019). "In the case of chronic kidney disease (CKD), the FGF23 level rises early in the course of the disease, stimulates urinary phosphate excretion and inhibits the activation of 25-hydroxyvitamin D (25D), and contributes to the development of secondary hyperparathyroidism." (PMID 31615432, 2019). "In patients with chronic kidney disease (CKD), circulating FGF23 is increased with decreasing renal function, and can reach up to 1000 times higher than normal levels." (PMID 31372314, 2019). "Mineral and bone metabolism disorders in chronic kidney disease (CKD-MBD)constitute a syndrome defined by changes in calcium, phosphorus (P), vitaminD and parathormone, fibroblast growth factor 23 (FGF-23) and its specificcofactor, Klotho." (PMID 30534856, 2019). "Patients with chronic kidney disease (CKD) have very high levels of FGF23 and may be the population suffering from the most adverse FGF23-related effects." (PMID 30909513, 2019). "In recent years, the importance of the role of enhanced circulating FGF23 on the development of cardiac remodeling was thoroughly demonstrated in patients with CKD and end-stage renal disease (ESRD)." (PMID 29892269, 2018). "In chronic kidney disease (CKD), FGF23 is increased in early stages of renal disease even before phosphate retention occurs." (PMID 30086150, 2018). "Kidney diseases are characterized by an impaired glomerular filtration rate and in the first stages of chronic kidney disease (CKD) the phosphate concentration in plasma is maintained by PTH and FGF23." (PMID 30037054, 2018). "In chronic kidney disease (CKD), hyperphosphatemia induces fibroblast growth factor-23 (FGF-23) expression that disturbs renal 1,25-dihydroxy vitamin D (1,25D) synthesis; thereby increasing parathyroid hormone (PTH) production." (PMID 30513912, 2018). "In patients with chronic kidney disease (CKD) or acute kidney injury (AKI), when glomerular filtration rate (GFR) falls to less than 60 ml/min, a rise in FGF-23 production by osteocytes and osteoblasts is one of the earliest changes." (PMID 30109232, 2018). "In early stages of chronic kidney disease (CKD), serum phosphate is normally maintained within the normal range owing to the compensatory increase in fibroblast growth factor-23 (FGF-23) and parathyroid hormone up until the estimated glomerular filtration rate (eGFR) reaching 30 mL/min/1.73 m2." (PMID 29850246, 2018). "This hypothesis offers fascinating prospects in terms of therapeutic interventions, specifically in patients with chronic kidney disease (CKD) in whom the FGF23 system is strongly stimulated and in whom left-ventricular dysfunction is a major disease burden." (PMID 30013515, 2018). "FGF23 and PTH are found to be at elevated levels in chronic kidney disease and end stage renal disease patients in response to elevated phosphate levels." (PMID 30333977, 2018). "In chronic kidney disease (CKD), a state of FG23 excess, FGF23 can also bind to FGFR4, independently of KL." (PMID 29085059, 2017).